ID1 (inhibitor of DNA binding 1)
Diseases named in the same sentence as ID1 in open-access papers (continued):
Sharing a sentence is not in itself a finding about the gene and the disease.
gastric cancer (continued). "In this study, we mainly investigated the feasibility of localized and sustained delivery of Id1-targeted siRNA incorporated within collagen, the characteristic of siRNA release profile, and its effect on growth and migration ability of gastric cancer cells both in vitro and in vivo." (PMID 27029190, 2016). "EGCG induces apoptosis and inhibits proliferation of poorly differentiated AGS gastric cancer cells, and Id1 may be one of the target genes regulated by EGCG in cancer inhibition." (PMID 23900621, 2013). "Id1 RNAi affected the phenotypic changes in AGS gastric cancer cells in a dose-dependent manner." (PMID 23900621, 2013). "Therefore, high Id1 expression is directly related to the malignant potential of gastric cancer cells." (PMID 23900621, 2013). "Our experiments proved that EGCG could play a role in inhibiting proliferation, promoting apoptosis, and affecting cell cycle of poorly differentiated AGS gastric cancer cells, which is closely related to down-regulation of Id1 expression." (PMID 23900621, 2013). "In summary, we found that the ID1 mRNA expression in bone marrow and peripheral blood is a reliable predictive marker for lymph node metastasis and peritoneal dissemination, which indicates a poor prognostic outlook in gastric cancer." (PMID 19491902, 2009). "In this study, we also examined the ID1 expression in primary lesion of gastric cancer cases." (PMID 19491902, 2009). "We also examined the ID1 expression of bone marrow carcinomatosis resulting from gastric cancer." (PMID 19491902, 2009). "Thus, ID1 is a bona fide predictive marker for both pathologic parameters, each of which is an established definitive prognostic indicator in gastric cancer." (PMID 19491902, 2009). "Therefore, we investigated the clinical significance of ID1 mRNA expression in bone marrow and peripheral samples in patients with gastric cancer." (PMID 19491902, 2009). "The level of the ID1 protein in gastric cancer tissues with a low degree of differentiation was higher than that in gastric cancer tissues with a high degree of differentiation, indicating that the expression of ID1 may be related to the occurrence and development of gastric cancer." (PMID 39619441, 2024). "Therefore, it is significant that the ID1 expression in bone marrow and peripheral blood can be used as a reliable marker before surgery to determine which gastric cancer patients are likely to have peritoneal dissemination mediated through lymph node metastasis." (PMID 19491902, 2009). "We obtained 43 DEGs with the adjusted p < 0.05 and | log2 FC)|>1, of which JUNB, ID1, CDKN1C, ID3, and BCAR3 were lowly expressed in gastric cancer tissues, and the remaining DEGs were highly expressed in gastric cancer tissues." (PMID 36467074, 2022). "In gastric cancer cells, the regulatory effect of PTBP3 on alternative splicing of the Id1 gene was investigated." (PMID 32974175, 2020). "Thus, Id1 may be an important target for gastric cancer therapy." (PMID 27029190, 2016). "Id1 participated in proliferation, apoptosis and other biological behavior of poorly differentiated AGS gastric cancer cells." (PMID 23900621, 2013). "One differentially expressed gene, Id1, in AGS gastric cancer cells before and after treatment with EGCG was screened out, and was verified subsequently." (PMID 23900621, 2013). "Furthermore, treatment with epigallocatechin-3-gallate, a catechin from tea, down-regulates Id1 mRNA and protein in poorly differentiated AGS gastric cancer cells." (PMID 28122577, 2017). "In gastric cancer, Id3, but not Id1, was a strong independent predictor for shorter overall survival." (PMID 23342268, 2012). "Co-suppression of ID1 and ID3 significantly reduces proliferation, invasiveness, anchorage-independent growth, and angiogenesis and increases apoptosis in small-cell lung cancer; moreover, targeting ID1 and ID3 reduces the formation of peritoneal metastases by gastric cancer cells." (PMID 34295890, 2021).
gastric cancer (continued). "Gastric adenocarcinoma shows Id1 up-regulation, whereas the metastatic tumors express lower Id1 levels than the primary tumors, suggesting that Id1 may not be determinant for gastric cancer metastasis." (PMID 28122577, 2017). "The current findings may suggest that ID1 is not a component of the aggregated cancer cells in the metastatic lymph nodes and peritoneal disseminated tumours, but instead plays a supportive role for gastric cancer cells to form lymph node metastasis and peritoneal dissemination." (PMID 19491902, 2009).
non-small cell lung carcinoma (15 papers, 2013 to 2025). A group of at least three distinct histological types of lung cancer, including non-small cell squamous cell carcinoma, adenocarcinoma, and large cell carcinoma. "In non-small cell lung cancer, miR-381 led to a suppression of tumor growth and chemoresistance by direct downregulation of differentiation 1 (ID1)." (PMID 30309377, 2018). "In patients with non small-cell lung cancer (NSCLC), high ID1 expression was associated with poor survival and resistance to chemotherapy or radiotherapy." (PMID 29169374, 2017). "It has also been reported that Id1 was immunohistochemically expressed in majority of non-small cell lung cancer (NSCLC) samples." (PMID 24378760, 2014). "Similarly, STMN3, a microtubule destabilizing protein, is induced by both nicotine and EGF in an ID1 dependent fashion, as well as can facilitate the proliferation, invasion and migration of non-small cell lung cancer." (PMID 37965307, 2023). "Furthermore, Id1 is overexpressed in non-small-cell lung carcinoma and exerts pro-inflammatory and tumor-promoting effects." (PMID 34950252, 2021). "However, the clinical significance and biological role of Id-1 in non-small cell lung cancer (NSCLC) remains unclear." (PMID 29233161, 2017). "We have studied, using monoclonal antibodies for immunohistochemistry, the Id1 and Id3 tumor epithelial expression in 17 patients with stage III-N2 non-small cell lung cancer (NSCLC) treated with definitive chemoradiotherapy." (PMID 23311395, 2013). "Additionally, ID1 and ID3 coexpression was correlated with a poor clinical outcome in patients with locally advanced non-small cell lung cancer treated with definitive chemoradiotherapy." (PMID 36443709, 2022). "Scutellaria flavonoids, especially the three prominent representatives (baicalin, baicalein, and wogonin), inhibited Id1 through the activation of Rap1-GTP binding and the dephosphorylation of AKT and Src in A549 cells, H1299 non-small-cell lung carcinoma cells, and murine A549 xenografts." (PMID 34950252, 2021). "Results from our gene expression profiling study are in broad agreement with previous studies performed on non-small-cell lung cancer (NSCLC) and head and neck squamous cell carcinoma (HNSCC), where greater than 95% of cases have been shown to overexpress BMP2, phosphorylated SMAD1/5, and Id1." (PMID 32708289, 2020).
breast tumors (14 papers, 2011 to 2025). "While there is no consensus as to the prognostic impact of ID2 expression in breast tumors, relatively high ID1 expression has consistently been associated with poor prognosis and, consequently, with invasive and metastatic capacities." (PMID 29666142, 2018). "Furthermore, it is important to note that increased MaSC activity caused by Id1 in mammary glands resulted in the formation of hyperplastic nodules and breast tumors." (PMID 25938540, 2015). "Among nine human breast tumors examined, only Id-1-expressing cells also expressed the 120 kDa gelatinase." (PMID 41303422, 2025). "In breast, overexpression of Id-1 in MMTV-Id-1 transgenic mice led to increased incidence of breast tumors of basal subtype (2 out of 69 at 24 months of age)." (PMID 34736527, 2021). "In spontaneous primary tumors of the breast in the MMTV-Her2/neu model, genetic analyses indicated that loss of Id1 and/or Id3 was insufficient to inhibit tumor growth and needed to be combined with suboptimal doses of chemotherapy to cause regression." (PMID 34031428, 2021). "It is worth noting that Stankic and colleagues recently identified ID1 as a critical regulator of breast tumor-initiating phenotype and metastatic colonization." (PMID 28611292, 2017). "Taken together, these findings suggest that Id1 induces basal marker-expressing breast tumor by increasing deregulation of mammary basal stem cells, thereby contributing to mammary tumorigenesis." (PMID 25938540, 2015). "To investigate the relationship between CCND1 and ID1 expression in primary breast tumours we used a previously published meta-analysis consisting of six groups of tumours on Affymetrix arrays totaling 1 107 samples." (PMID 21955753, 2011). "A meta-analysis of primary breast tumours revealed significant associations between CCND1, ID1, CDH1 (E-cadherin) and recurrence-free survival." (PMID 21955753, 2011). "This concept is supported by an earlier publication by Minn and colleagues who listed ID1 as a transcriptional regulator of the lung metastasis gene signature of human primary breast tumours as well as MDA‐MB‐231 cells injected orthotopically into the mammary fat pad of mice." (PMID 40116596, 2025). "Herein, using MMTV-Id1 transgenic mice, we identified that Id1 plays a crucial role in the regulation of normal and malignant mammary stem cells by activating the Wnt/c-Myc pathway, thereby contributing to basal marker-positive breast tumor development." (PMID 25938540, 2015). "Interestingly, the expression of genes (GFRA1, ID1, ABCG2) implicated in the regulation of hematopoietic progenitor cells was found to be elevated in bone metastases compared with the primary breast tumors that had relapsed to bone." (PMID 23174366, 2012). "Upregulation of Id4 transcripts were also previously observed in MDCK cells overexpressing E47, although to a lower extent than Id1, supporting also the correlation between ID4 and TCF3 upregulation in basal breast tumours." (PMID 23555842, 2013). "In the breast tumor microenvironment, TGF-β is oncogenic by priming cancer cells for metastasis to the lungs, facilitating the dissemination and colonization of cancer cells that have undergone EMT via ID1 mediated mesenchymal to epithelial transition (MET)." (PMID 36207293, 2022). "For example, different breast tumors failed to grow and/or metastasize in Id1 (+/−) Id3 (−/−) knockout mice." (PMID 23311395, 2013). "Among non-TN breast tumors, only 1 out of 105 was positive for Id1 expression." (PMID 41303422, 2025). "Whether ID1 and ID4 play non-redundant or complementary actions on EMT and/or the basal phenotype and chemoresistance of breast tumours remains to be established in future studies." (PMID 23555842, 2013).
cervical carcinoma (14 papers, 2004 to 2025). A carcinoma arising from either the exocervical squamous epithelium or the endocervical glandular epithelium. "In our present report, we demonstrate for the first time, the co-expression of LMP1 and E6 of EBV and high-risk HPVs, respectively, which is associated with Id-1 overexpression in human cervical cancer samples." (PMID 30035100, 2018). "On the other hand, this investigation reported that the presence of high-risk HPVs is correlated with Id-1 gene over-expression in human breast cancers, as it was revealed in human cervical cancer." (PMID 24765613, 2014). "On the other hand, this investigation reported that the presence of high-risk HPVs is correlated with Id-1 gene over-expression in 95.23% of human cervical cancers, which are invasive carcinomas in the majority of cases." (PMID 24765613, 2014). "Over expression of ID-1 is associated with more aggressive behavior of tumour cells in cervical cancer." (PMID 19002177, 2008). "Accordingly, it is possible that EBV and high-risk HPV cooperate to upregulate the expression of Id-1 in human cervical cancer, which could enhance rapidly the progression of this cancer into invasive and metastatic form." (PMID 30035100, 2018). "Therefore, in this study, we evaluated the co-presence of these viruses and their association with Id-1 expression in cervical cancers in Syrian women." (PMID 30035100, 2018). "However, herein, it is important to highlight that few investigations, including one from our lab, have pointed out that the presence of E6/E7 of high-risk HPVs is linked with Id-1 overexpression in human cervical cancer cells." (PMID 30035100, 2018). "Accordingly, it was displayed that Id-1, a member of the helix–loop–helix transcription factor family, is expressed in the majority of invasive cervical carcinomas." (PMID 24765613, 2014). "Previous studies reported, expression of ID-1 was shown as an independent prognostic factor in cervical cancer with long-time follow-up, even more significant in early-stage disease." (PMID 19002177, 2008). "Id-1 overexpression has been reported in several human primary cancers including pancreatic, breast and cervical cancers." (PMID 15026801, 2004). "In another study on cervical cancer, Id1-induced activation of the PI3K pathway could be followed to downstream target NFkBp65." (PMID 41303422, 2025). "Moreover, the study revealed that E6 expression of high-risk HPVs correlates with overexpression of Id-1, indicating the progression of HPV-positive cervical cancer via Id-1 regulation." (PMID 36422631, 2022). "Co-expression of Id1 and nuclear NF-κB p65 promotes progression and malignancy of cervical cancer." (PMID 32410828, 2020). "Furthermore, vinblastine (VBL), a key microtubule inhibitor, was also confirmed that it downregulated Id1 in VBL-treated human cervical carcinoma cells." (PMID 32410828, 2020). "We have developed a cell-based assay to monitor BMP signaling by stably transfecting a BMP-responsive human cervical carcinoma cell line (C33A) with a reporter construct in which the expression of luciferase is driven by a multimerized BMP-responsive element from the Id1 promoter." (PMID 23527084, 2013). "Study showed that ANXA1 down-regulated Id1 gene expression and the Id1 pathway gene, BMPR1B, in cervical cancer." (PMID 32410828, 2020). "Because of the correlation of Id1 expression and human papillomavirus (HPV)-induced cervical cancer, it is suggested, that Id1 also plays a role in HPV-related cervical carcinogenesis." (PMID 28122577, 2017). "Therefore, E6/E7 of high-risk HPV can deregulate several oncogenes, such as P-cadherin, fascin, Id-1, IGF-R1, and EGF-R which are known to enhance the progression of human cervical cancer." (PMID 20862378, 2010). "However, there are no studies regarding the EBV onco-proteins and Id-1 in human cervical cancer." (PMID 30035100, 2018).
cervical carcinoma (continued). "In cervical cancer, the T-box transcription factor 3 (TBX3) promotes EMT, and its expression correlates with Id1 mRNA and protein levels, although it has not yet been confirmed whether TBX3 regulates Id1 directly." (PMID 41303422, 2025).
leukemia (14 papers, 2012 to 2025). A malignant (clonal) hematologic disorder, involving hematopoietic stem cells and characterized by the presence of primitive or atypical myeloid or lymphoid cells in the bone marrow and the blood. "We further demonstrated that 5-demethyl NOB-induced ID1 reduction was associated with the inhibition of leukemia cell growth." (PMID 35806401, 2022). "In AML, ID1 is highly expressed in leukemia cells and is associated with poor prognosis in patients." (PMID 35806401, 2022). "Furthermore, conditional loss of Id1 in established AML-ETO-leukemia’s slows the development of leukemia and promotes animal survival, suggesting that Id1 is also required for the maintenance of leukemia." (PMID 35990659, 2022). "RUNX1 mutant directly enhanced the transcriptional activity of HIF-1α and increased its target gene expression such as ID1 which could be a potential target for future therapy in ASXL1-mutated leukemia." (PMID 31640815, 2019). "However, aberrant ID1 expression, driven by pathogenic mechanisms, such as gene mutations or oncogenic kinases, contributes to the initiation and progression of various blood disorders, particularly leukemia." (PMID 41146039, 2025). "The transgenic expression of Id1 in thymocytes was found to change the normal distribution of the thymocyte population at the DN and later stages in a way that is highly compatible with a hematopoietic developmental block, which is a frequent cause of leukemia." (PMID 41303422, 2025). "Id1 deletion can abrogate and slow down leukemia initiation, and markedly prolong the survival time of the exon9a isoform of AML-ETO (AE9a) mice." (PMID 41146039, 2025). "Mistry and colleagues have demonstrated that newly developed small-molecule inhibitors of USP1 lead to the breakdown of ID1 and are harmful to leukemia cells." (PMID 39048945, 2024). "In MLL-AF9 leukemia, P21 is silenced by Inhibitor of DNA binding 1 (ID1), which is critical for MLL-AF9 leukemogenesis." (PMID 35269391, 2022). "It has been shown that the ID1 transcriptional inhibitor-MMP9 axis can enhance the invasiveness of BCR-ABL1 transformed leukemia cells." (PMID 35111390, 2022). "The delay in Id1-/- MLL-AF9 leukemia was reversed in FL cells that lack p21, which is consistent with previous studies demonstrating that ID proteins promote HSPC proliferation by inhibiting the E-Cdki pathway." (PMID 35990659, 2022). "The overexpression of ID1 was also shown to promote the growth of leukemia cells, inhibit apoptosis, and increase resistance to decitabine." (PMID 36135094, 2022). "In our previous study, we found that miR-29b acts as a tumor suppressor in leukemia cells, while ID1 acts as an oncogene (unpublished data)." (PMID 36135094, 2022). "Taken together, these studies provide evidence that ID1 is required for the initiation and progression of oncogene driven leukemias." (PMID 35990659, 2022). "In other studies, the progression of leukemia was significantly delayed after transplantation of MLL-AF9-transduced Id1-/- FL cells compared to MLL-AF9-transduced Id1+/+ fetal liver cells." (PMID 35990659, 2022). "It is different from other tumors that the differential role of Id1 in MLL-AF9-driven leukemia is basing on cell of origin." (PMID 32410828, 2020). "As to the therapy targeting Id1 in leukemia, pimozide, a known USP1 inhibitor was proved effective in inhibiting the growth of primary AML patient-derived leukemic cells." (PMID 32410828, 2020). "To evaluate if Id1 overexpression correlates with the development of leukemia in mice, we examined Id1 expression in the spleen, liver, and BM of mice induced by ASXL1-R693X, RUNX1-R135T, and combination of ASXL1 and RUNX1 mutants as well as control." (PMID 31640815, 2019). "This study demonstrated that Id1 promoter is transcriptionally inhibited by FoxO3a, leading to differentiation of BCR-ABL transformed cells, suggesting that Id1 is essential for maintaining the leukemia phenotype." (PMID 23259070, 2012).